VWA2 (von Willebrand factor A domain containing 2)
Synonyms: AMACO; CCSP-2; FLJ45857; FLJ16213; NET42; CCSP2
Tractability: Antibody: UniProt places it where antibodies can reach, with medium confidence; UniProt predicts a signal peptide or a membrane-spanning region; its Gene Ontology location is reachable by antibodies, with medium confidence.
Gene: Protein-coding gene on chromosome 10 (114,239,254 to 114,294,489, forward strand). Ensembl gene ENSG00000165816.
Subcellular location: Secreted
Gene Ontology:
Molecular function: identical protein binding; protein binding; calcium ion binding
Biological process: regulation of insulin receptor signaling pathway; calcium-independent cell-matrix adhesion
Cellular component: extracellular exosome; extracellular region; basement membrane
Genetic constraint (gnomAD): Loss-of-function variants: 71 observed, 69.89 expected, observed/expected ratio (o/e) 1.02, 90% interval 0.84 to 1.24. The upper end of that interval is the gene's LOEUF score, 1.24, which puts it in group 5 of 6, group 1 being the genes least tolerant of losing a copy. Missense variants: 1,003 observed, 1,018.6 expected, observed/expected ratio (o/e) 0.98, 90% interval 0.93 to 1.04. Synonymous variants: 403 observed, 434.46 expected, observed/expected ratio (o/e) 0.93, 90% interval 0.85 to 1.01.
Homologues: Orthologues: chimpanzee VWA2 (98% identical), macaque VWA2 (91% identical), rabbit VWA2 (83% identical), dog VWA2 (82% identical), mouse Vwa2 (80% identical), rat Vwa2 (79% identical), pig VWA2 (79% identical), guinea pig VWA2 (69% identical), tropical clawed frog vwa2 (54% identical), zebrafish vwa2 (50% identical). Paralogues in human: COL12A1 (25% identical), COL6A6 (23% identical), COL6A3 (23% identical), COL6A5 (22% identical), COL14A1 (22% identical), MATN2 (20% identical), MATN4 (18% identical), MATN1 (16% identical), COCH (14% identical), MATN3 (10% identical), VWA1 (10% identical), VIT (8% identical).
Diseases named in the same sentence as VWA2 in open-access papers:
VWA2 is named in the same sentence as 16 diseases in open-access papers, as found by Europe PMC text mining. Sharing a sentence is not in itself a finding about the gene and the disease. The quoted sentences say what the papers report.
colon cancer (4 papers, 2019 to 2024). "In humans, AMACO was also referred to as colon cancer secreted protein-2 (CCSP-2), as it was found to be upregulated in colon cancer, and epigenetic and transcriptional dysregulation of VWA2 was found to be associated with an MYC-driven oncogenic program in colorectal cancer." (PMID 37047755, 2023).
colorectal cancer (4 papers, 2018 to 2025). A primary or metastatic malignant neoplasm that affects the colon or rectum. "VWA2 encodes AMACO, a secreted protein up-regulated in most colorectal carcinomas (CRC), constituting a promising biomarker." (PMID 30038405, 2018). "VWA2 (EC) has recently been found to have predictive and prognostic potential in colorectal cancer, although the biological role of this extracellular protein is not fully understood." (PMID 40778374, 2025). "We analyzed VWA2 methylation by bisulfite sequencing in 7 colorectal cancer cell lines." (PMID 30038405, 2018). "In colorectal cancer (CRC), a fusion mRNA involving the gene TCF7L2 and exons 1 to 4 of VWA2 has been identified." (PMID 30038405, 2018).
adenoma (2 papers, 2018 to 2019). A neoplasm arising from the epithelium. "VWA2 had been found to be over-expressed in the majority of colorectal tumors, including adenomas and carcinomas." (PMID 30038405, 2018).
rectal cancer (1 paper, 2018). A primary or metastatic malignant neoplasm that affects the rectum. "The analysis of VWA2 expression in normal and tumor tissues from 34 different cancer cohorts with RNAseq data available at the TCGA revealed that somatic over-expression of this gene is particularly strong and frequent in colon and rectal cancers." (PMID 30038405, 2018).
tumor (4 papers, 2015 to 2021). "In addition to the two positive control fusions involving TCF7L2, another TCF7L2 fusion with VWA2 as a novel upstream fusion partner was identified in one tumor sample." (PMID 26474385, 2015).
cancer (3 papers, 2018 to 2021). A tumor composed of atypical neoplastic, often pleomorphic cells that invade other tissues. "The association between VWA2 DNA methylation and transcriptional expression was studied only in primary cancer derived cell lines, after excluding the lymph-node metastatic cell line SW620." (PMID 30038405, 2018). "We also performed a comparative analysis of VWA2 overexpression in 36 different types of cancer, exploring the data from the The Cancer Genome Atlas (TCGA)." (PMID 30038405, 2018). "Paradoxically, HT29 and HCT116 cell lines exhibited strong hypermethylation and transcriptional silencing of VWA2, essentially the opposite phenomenon to that observed in primary cancers." (PMID 30038405, 2018). "Transcriptional up-regulation of VWA2 is extremely frequent (78%) and strong (average fold change >15) in CRC, but not in other types of cancer." (PMID 30038405, 2018).
VWA2 also shares sentences with these, for which no sentence is quoted: adenocarcinoma (2 papers); colon adenoma (2); colorectal tumor (2); bullous pemphigoid (1); colorectal adenocarcinoma (1); colorectal adenoma (1); Fraser syndrome (1); head and neck squamous cell carcinoma (1); kidney cancer (1); lung squamous cell carcinoma (1).